CD40 (CD40 molecule)
Diseases named in the same sentence as CD40 in open-access papers (continued):
Sharing a sentence is not in itself a finding about the gene and the disease.
infection (continued). "During infection, no obvious modulation of CD40 and CD86 on LN MΦs was observed." (PMID 38012553, 2023). "Interestingly, pDC showed increased MFI for CD40, CD80, CD86, and MHC-II on the molecules positive pDC, respectively, after BCG immunization, especially at 4 h and 12 h post-infection, suggesting high expression levels of these molecules on the limited positive pDC." (PMID 36977141, 2023). "No obvious change in CD40 or CD86 was detected in LN MΦs during infection." (PMID 38012553, 2023). "For all classes of potential APCs at the infection site (i.e., monocytes, macrophages, and DCs), expression of CD40 and CD80 on both T. cruzi-infected and noninfected cells was at the level of naive cells through 4 days postinfection and became significantly different by day 6 postinfection." (PMID 36695605, 2023). "Furthermore, macrophages increased the expression of activation markers (CD80, CD86 and CD40) that was more evident at week 10 after infection while DCs of Treg depleted mice increased the expression of CD86 and CD40 at week 6 and CD80 and CD40 at week 10 after infection." (PMID 30410119, 2018). "No obvious regulation of CD40 or CD54 on DCs was observed during infection." (PMID 29940854, 2018). "Although the CD40/STING/IFN-I mechanism may not play an important role in some infections, it likely represents one of the possible protective mechanisms in human infections considering the potentially large number of P. falciparum strains in the field." (PMID 27716849, 2016). "Although the frequency of cells harboring the virus was indistinguishable at 16 dpi, CD40-/- B cells were present at reduced frequencies in the germinal centers and the number of CD40-/- B cells harboring latent virus decreased at late times after infection." (PMID 27582728, 2016). "Similarly to what we observed in DC2.4 cells, expression of CD40 was not altered in BMDC cells in either condition of infection." (PMID 25255446, 2014). "gondii activity was the same regardless of whether CD40 ligation took place before or after infection (not shown)." (PMID 23990781, 2013). "Costimulatory molecules (CD80, CD86, CD40, GITR, and ICOS), adhesion molecules (VCAM-1 and P-selectin), and signaling molecules involved in cytokine regulation (Tbx21 and Socs1) were also increased with Hb infection and decreased with anti-IL-7Rα M595 treatment in a dose-dependent manner." (PMID 23057802, 2012). "It has been suggested that signaling downstream of CD40 may perpetuate IL-10 production and enhance productive infection of macrophages but this has not been evaluated in DCs." (PMID 22911108, 2012). "Consistently, CD23 expression following infection with T. gondii parasites may be due to their ability to induce the transcription factor STAT6, which is involved in the induction of Th-2 gene promotion including CD40, CD23 and IgE." (PMID 21526166, 2011). "Finally, they represented diverse molecular classes – cytokines (TNF, IL-12p40, IL-6, IL-10, GM-CSF), chemokines (RANTES, MCP-1), enzymes (iNOS, cyclooxygenase [COX] 2) and cell-surface co-stimulatory proteins (Delta-4, CD40, GITRL) – with known roles in immune responses to infection." (PMID 21170273, 2010). "Interestingly, SAG, unlike LPS or TNFα, upregulated CD40 expression on DCs even after LD infection." (PMID 33370418, 2020). "Interestingly, CD40 was not affected by infection with either SFTSV or UV-inactivated SFTSV." (PMID 31156641, 2019). "SFTSV infection of activated macrophages resulted in the down-regulation of surface HLA-DR and CD86 but not CD40." (PMID 31156641, 2019). "Previously, expression of CD40 and CD40L on PBMCs was increased in cows naturally infected with MAP, regardless of stage of infection, upon stimulation of cells with live MAP." (PMID 27093613, 2016). "Administered before infection, neither anti-CR1 (CD35) nor anti-CR3 (CD11b) affected the stimulatory capacity of monocytes, as evaluated by expression of CD86, CD40 and HLA-DR (data not shown)." (PMID 25061945, 2014).
infection (continued). "Flow cytometry analysis of infected cells did not reveal a statistically significant increase in CD40, CD80 and CD86 surface expression in DCs infected with btpB mutant when compared to the wild type at 8 h post-infection." (PMID 23847770, 2013). "Flow cytometry analysis of cell surface expression markers CD40, CD54, CD80, CD83, CD86 and HLA DR in infected DC revealed significant (p < 0.05) up regulation following infection with M. tuberculosis in comparison to immature DC with no stimulation." (PMID 21777464, 2011). "CD40 and CD86 were increasingly expressed during the course of infection (data not shown); in contrast, CD80 failed to be upregulated." (PMID 19436710, 2009). "The absence of CD28, CD40, CD40L, CD80/CD86 or 4-1BBL did either not affect viral replication in the early phase of infection or early viral titers were rather increased." (PMID 19621080, 2009). "For late P. yoelii infection, the expression of CD40 and CD86 on CD11c+ splenocytes was not significantly upregulated in response to parasite infection (average parasitaemia, 21.62)." (PMID 19077314, 2008). "In fact, although we observed significantly lower baseline levels of the MHC II and costimulatory molecules, CD86 and CD40 on DCs in the absence of TLR4, the maturation and induction of these molecules was comparable to that of cells expressing TLR4 in response to hMPV infection." (PMID 24205331, 2013). "In addition, in the absence of CD40, CD40L or CD80/CD86, viral reactivation in the lungs was observed at later time points after infection." (PMID 19621080, 2009). "At 6 h after in vitro infection, microglia cells infected with C. krusei and C. parapsilosis presented a significantly higher expression of MHC II, and all species displayed increased expression of CD40 co-stimulatory molecule in comparison to non-infected microglia cells (control—CTL)." (PMID 35448617, 2022). "Significant (p < 0.05) up regulation in cell surface expression of CD40, CD80, CD54 and MHC class II and CD86 and CD83 were observed both in LPS stimulated and H37Rv infected in comparison to negative control DC with media alone without any stimulation/infection." (PMID 21777464, 2011).
cardiovascular disease (18 papers, 2012 to 2025). "Clinically, CD40L was proposed as biomarker of atherothrombosis, while its receptor CD40 associates with cardiovascular disease in GWAS." (PMID 28676852, 2017). "All together, these clinical findings have established a strong association between CD40L/CD40 signaling and cardiovascular disease, particularly in the setting of acute cardiovascular events and unstable atherosclerotic plaques." (PMID 28676852, 2017). "The majority of the inflammatory proteins that were found to be significantly elevated have been associated with increased cardiovascular disease such as, interleukin-5, cluster of differentiation 40 (CD40) and interleukin-1beta31, whilst FGF8 has been more associated with vascular remodeling." (PMID 32179763, 2020). "On the other hand, targeting downstream molecules in the CD40 signaling pathway has shown to be both effective and safe for treating cardiovascular disease." (PMID 39899926, 2025). "Further, CD40 decreases NO and increases ROS production by endothelial cells, inhibiting angiogenesis and contributing to the pathogenesis of cardiovascular diseases." (PMID 32471156, 2020). "Both CD154 and CD40 are potential therapeutic targets of cardiovascular disease." (PMID 33986658, 2020). "More importantly, bazedoxifene protected VECs from TNF-α-induced damage, suggesting that bazedoxifene may play a protective role in cardiovascular diseases through regulating the complex network connecting CD40, STAT3, AKT, ERK, and NF-κB signaling." (PMID 33381228, 2020). "The SNP on the CD40 gene, rs1883832, has been associated with ACS in the presence of the major C allele and has been related with decreased levels of sCD40 in the presence of the minor T allele and risk of cardiovascular diseases." (PMID 31183392, 2019). "On a side note, the difference described between males and females in the prevalence in cardiovascular diseases might be in part due to a difference in CD40 on human macrophages." (PMID 27146510, 2016). "The role of the CD40 and CD154 pathway has been extensively investigated in many diseases including cardiovascular diseases." (PMID 22384195, 2012). "Although it was shown that CD40 can mediate macrophage function, its exact role in macrophage biology has not gained much attention in cardiovascular disease." (PMID 27146510, 2016). "In cardiovascular diseases, blocking CD40 signaling has never been tested in clinical trials." (PMID 27146510, 2016).
bacterial infection (14 papers, 2012 to 2024). "Various stimuli were used: anti-CD40 monoclonal antibody to activate B cell signaling; lipopolysaccharide (LPS) to mimic bacterial infection; and IgM antibodies, which elicit aggregation of the B cell receptor and mimic the initial signal to activate B cells." (PMID 38422022, 2024). "After examination of coactivators in monocytes after bacterial infection, we found reduced expression of coactivators (i.e., CD40, CD86, MHC-II, and CD14) from TSC1 KO mice and WT mice." (PMID 27746591, 2016). "From our bacterial infection list, we found that the expression of CD40 was a predictor of death in septic children (GSE2644031)." (PMID 26302899, 2015). "The bacterial infection in FHN-affected bone could be activating CD40 as a regulator of further downstream immune-related responses." (PMID 37233703, 2023). "CD40 expression was shown to be induced by bacterial infection in human and mouse osteoblast cells." (PMID 37233703, 2023). "In the bacterial infection model, DC expression of CD83, CD40 and CD86 recovered by D5 to baseline levels." (PMID 32180339, 2020). "Mean fluorescence values of MHC II, CD40, and CD80 in O. tsutsugamushi-infected DCs increased by more than 2 fold when compared to those of un-stimulated immature DCs, indicating that bacterial infection induced DC activation." (PMID 23301113, 2013). "Moreover, those authors observed a marked increase in the expression of the microglial surface antigens CD40 and MHC II in the hippocampus of adult animals in response to early-life bacterial infection." (PMID 25814933, 2015). "Relative to medium alone, all bacterial infections induced marked changes in the cellular morphology of the iMDDCs, consistent with those occurring in response to the potent inducer (CD40-ligation) of DC maturation (data not shown)." (PMID 23424672, 2013). "However, a synergistic effect of TLRs and CD40 during bacterial infection is not known." (PMID 26441965, 2015).
neurodegenerative disease (9 papers, 2011 to 2025). A disorder of the central nervous system characterized by gradual and progressive loss of neural tissue and neurologic function. "Involvement of CD40 in activation of pathogenic cascade that will result in neuronal cell death is documented in a wide variety of neuroinflammatory and neurodegenerative diseases." (PMID 25972624, 2015). "Decreased expression of pro-inflammatory genes, which are associated with neurodegenerative disease or astrocyte and microglia phenotypes Cd40, C1qB, Cd68, Cd45, Aqp-4, Il1α, Fkbp5, Ggta1, Cd16, H2-T23, and Serping1, was observed following C-32:6 treatment and C1qC, Tspo, and Gbp2 with FFA C-34:6." (PMID 37740008, 2023). "Furthermore, increased CD40 expression has been linked with several neurodegenerative diseases and observed in microglial populations around Aβ plaques." (PMID 37830592, 2023). "This immunosuppressive effect was particularly striking for CD40, a key regulator of microglial reactivity in infectious and neurodegenerative diseases (Ponomarev, Shriver, and Dittel 2006)." (PMID 39780484, 2025). "This immunosuppressive effect was particularly striking for CD40, a key regulator of microglial activation in infectious and neurodegenerative diseases." (PMID 39131388, 2024). "In this study, CD48 and CD40 gene expression in AD, a neurodegenerative disease, was analyzed to infer this link." (PMID 36520044, 2023). "The aberrant expression of CD40, a co-stimulatory receptor found on the antigen-presenting cells, is involved in the pathogenesis of various degenerative diseases." (PMID 28187742, 2017). "Twenty-seven of these associations are known disease loci reported in GWAS, including APOE, MME, CD2AP, CD33 and IL34 for AD, and CD40, CD58, EVI5, IL7R and STAT3 for MS, and 23 associations represent previously unreported genetic associations with neurodegenerative diseases." (PMID 40037332, 2025). "Therefore, it seems to us that a combination of anti-CD40 antibody and TNFR1 blockers may need for neurodegenerative disease therapy like MS." (PMID 21410936, 2011).
hematological malignancies (7 papers, 2018 to 2025). "CD40 is strongly expressed on the surface of many hematological malignancies and CD40 expression can also be quite high on solid tumors." (PMID 36361658, 2022). "Dacetuzumab is a humanized IgG1 anti-CD40 antibody considered as a weak agonist of CD40; several clinical trials have shown its efficiency in treatment of hematological malignancies." (PMID 28660349, 2018). "However, CD40 is also expressed on B-cells and CD40 therapeutics are also being considered for use in various hematological malignancies." (PMID 34458756, 2020).
infectious disease (7 papers, 2014 to 2024). A disorder directly resulting from the presence and activity of a microbial, viral, or parasitic agent in humans. "Several CD40-targeting vaccines have been demonstrated to be immunogenic against different infectious diseases." (PMID 36016929, 2022). "Anti-CD40 targeting vaccines currently in development against infectious diseases." (PMID 36016929, 2022).
kidney disease (7 papers, 2015 to 2025). "Despite this wealth of knowledge of CD40 expression, the contribution of these cell types to CD40 signaling that underlie renal disease is still unclear." (PMID 26623936, 2015). "Their upregulation of CD40 contributes to their inflammatory response and the following fibrotic process in kidney disease." (PMID 36902810, 2023). "Targeting CD40 has been demonstrated to be a promising approach and a potential therapeutic method for treating renal disease." (PMID 33202988, 2020). "The cluster of differentiation 40 (CD40) is activated by the CD40 ligand (CD40L) in a variety of diverse cells types and regulates important processes associated with kidney disease." (PMID 33202988, 2020). "The importance of CD40 in the development of renal disease and allograft rejection following kidney transplantation has focused on its role as an immune co-stimulatory molecule that is associated with adaptive immunity." (PMID 33202988, 2020). "Levels of the circulating CD40 receptor (sCD40), sCD40L, and local CD40 expression are tightly related to renal injury in different types of kidney disease." (PMID 33202988, 2020). "The CD40/CD40L signaling axis plays important roles in the progression of a wide range of kidney diseases." (PMID 33202988, 2020). "Here, we summarize the studies focused on the CD40/CD40L axis in immune cells which contribute to local inflammation in kidney disease." (PMID 33202988, 2020). "In this review, we describe the outcomes of recent studies and summarize the potential therapeutic methods for kidney disease which target CD40." (PMID 33202988, 2020). "To explore the role of CD40 in a model of renal disease, we evaluated CD40 ASO treatment in DOX nephropathy." (PMID 26623936, 2015). "We also found, using the Olink proteomic platform, that TNF-α and TMAO enhanced the secretion of additional inflammatory-and growth mediators associated with kidney disease; VEGFA, GDNF, CDCP1, OPG, uPA, AXIN1, MMP-1, MMP-10, PD-L1, HGF, Flt3L, 4E-BP1, CD40, CASP-8, ADA, TNFRSF9, TWEAK44–61." (PMID 38643262, 2024). "As numerous reports are accumulating which implicate CD40/CD40L signaling in kidney disease, below we have summarized the recent studies to provide new insights and improve our understanding of the role of CD40 signaling in the development and progression of renal disease." (PMID 33202988, 2020). "Here, CD40 has been considered as an important mediator regulating inflammatory and fibrotic processes and thus, more studies have focused on the role of CD40 in kidney cells and its implications involved in the development of kidney disease." (PMID 33202988, 2020). "Therefore, targeting CD40 may be a promising approach and a potential therapeutic method for the treatment of kidney disease." (PMID 40243751, 2025). "The involvement of CD40 in immune cells has been associated with local kidney inflammatory state, and CD40/CD40L signaling in various renal cell types has been implicated in mediating glomerular permeability, interstitial inflammation, and fibrosis in kidney disease." (PMID 40243751, 2025). "In a study using the doxorubicin (DOX)-induced nephropathy model in C57BL/6 mice, CD40 expression was shown to be elevated in renal glomeruli following injury." (PMID 33202988, 2020). "CD40/CD40L signaling in various kidney cell types has demonstrable effects on the mediation of glomeruli permeability, interstitial inflammation, and fibrosis during kidney disease." (PMID 33202988, 2020). "Although the potential for adverse CD40 signaling in kidney cells has been reported in several studies, a summary of those studies focusing on the role of CD40 signaling in the development of kidney disease is lacking." (PMID 33202988, 2020). "Unilateral ureter obstruction (UUO) studies were performed to determine the efficacy of CD40 ASO treatment to blunt CD40-dependent inflammation in a renal disease model not driven by glomerular injury." (PMID 26623936, 2015).
kidney disease (continued). "Some studies found that CD40L in patients with kidney disease was significantly lower than that in normal people by measuring CD40L on TFH cells, indicating that the decrease in blood IgG level in patients with kidney disease was related to the weakening of CD40/CD40L response." (PMID 38152332, 2023).
neurological disorders (5 papers, 2014 to 2024). "Both cases present the opportunity to expand and repurpose current CD40 immunotherapies in future translational research as new therapeutic avenues to treat neurological disease." (PMID 35456932, 2022). "Therapies targeting the CD40 axis with potential applications for the treatment of neurological disease (Clinical Trials, 2011—Present)." (PMID 35456932, 2022). "Considering that activation of CD40 receptor in microglia leads to expression of iNOS and production of TNF-α and other proinflammatory molecules, benfotiamine's ability to suppress CD40 expression can alleviate inflammation in neurological disorders." (PMID 26388737, 2015). "Furthermore, EVPs in the CSF with CD40 or CD44 present on their surface may potentially play functional roles in the immunopathogenesis of neurological diseases of viral etiology." (PMID 37622115, 2023). "However, the role of CD40 in neurological disease of non-infectious etiology is unclear." (PMID 35456932, 2022).
adenocarcinoma (4 papers, 2015 to 2023). A common cancer characterized by the presence of malignant glandular cells. "CD40 gene overexpression was correlated with improved five-year overall survival (OS) (p < 0.001), while increased BAFFR and LTβR mRNA levels were associated with worse OS in patients with adenocarcinomas (p < 0.001 and p < 0.001, respectively)." (PMID 31137630, 2019). "The most significant finding was that of CD40 (Q-value = 3.36 × 10−4), whose Spearman's correlation was much more negative in adenocarcinoma samples (rho = −0.66) than in matched normal controls (rho = 0.25), and whose expression was significantly higher in normal samples (P-value = 2.82 × 10−4)." (PMID 26029238, 2015).